TSC1 (TSC complex subunit 1)
Diseases named in the same sentence as TSC1 in open-access papers (continued):
Sharing a sentence is not in itself a finding about the gene and the disease.
tuberous sclerosis (continued). "Tuberous sclerosis complex is a genetic disease caused by either TSC1 or TSC2 mutation, leading to mTORC1 hyperactivation, and most patients with this disease have TSC2 mutations." (PMID 30266942, 2018). "Tuberous sclerosis results from mutations in TSC1 and TSC2, which are direct negative regulators of the mTORC1 complex." (PMID 30083288, 2018). "The tuberous sclerosis complex is associated with mutations in the TSC1 (on chromosome 9) or TSC2 (on chromosome 16) genes encoding for hamartin or tuberin, respectively, and shows autosomal dominant inheritance with variable penetrance." (PMID 30123932, 2018). "Tuberous sclerosis is caused by mutations in either Tuberous Sclerosis 1/2 (TSC1/TCS2), where up to 61% of patients express autistic behaviors." (PMID 28420080, 2017). "Thefollowing keywords were used: TSC1 mutations; TSC2mutations; tuberous sclerosis complex; TSC mutations;TSC molecular analysis; genotype-phenotype correlation ontuberous sclerosis." (PMID 28222202, 2017). "Tuberous sclerosis is caused by mutations in one of two tumor suppressor genes:TSC1 (9q34) and TSC2 (16p13.3)." (PMID 28222202, 2017). "Such mutations of TSC1 or TSC2 cause tuberous sclerosis, a multisystem disorder associated with tumor formation in the brain, heart, lung, kidney, or eye." (PMID 28445147, 2017). "Tuberous sclerosis (TSC) is an inherited disease caused by mutations in TSC1 or TSC2 that lead to aberrant activation of mTOR and development of tumours in multiple organs." (PMID 28938574, 2017). "Akt inhibits the activity of the TSC1/TSC2 (proteins harboring mutations in tuberous sclerosis) complex, a negative regulator of mammalian target of rapamaycin (mTOR), which regulates autophagy." (PMID 27911875, 2016). "Tuberous sclerosis (TSC) is a monogenic disease resulting from defects of the TSC1 or TSC2 genes, which encode the proteins forming hamartin-tuberin tumor suppressor complex, the mammalian target of rapamycin complex (mTOR)." (PMID 27680012, 2016). "Tuberous sclerosis complex is an autosomal dominant disorder caused by mutations in either the TSC1 or TSC2 gene." (PMID 27458336, 2016). "Mutations in either the tsc1 or the tsc2 genes cause the hamartomatous syndrome tuberous sclerosis complex (TSC)." (PMID 26536660, 2015). "Tuberous sclerosis is an autosomal dominant genetic disorder that arises from germ line mutations in TSC1 or TSC2, which encode hamartin and tuberin, respectively." (PMID 26943379, 2015). "Mutations in TSC1 or TSC2 cause the human genetic disease Tuberous Sclerosis Complex (TSC), and studies in both mouse models and human TSC-related tumors demonstrated that mTORC1 was highly activated in these tumors." (PMID 26137524, 2015). "The Drosophila Tuberous sclerosis (dTsc1 and dTsc2) is homologs of TSC1 and TSC2, which are mutated in patients with Tuberous Sclerosis complex (OMIM 191100; OMIM 191092)." (PMID 26089803, 2015). "In brief, heterozygous mutations in the TSC1 or TSC2 gene cause tuberous sclerosis, a multisystem disorder, which is associated with autism in 20–60% of cases." (PMID 25114803, 2014). "Recent studies have linked Tsc1/2 dysregulation to cognitive deficits associated with tuberous sclerosis and identified this gene as a potential target to treat autism." (PMID 23927422, 2013). "Tuberous sclerosis complex is exclusively associated with mutations in either the TSC1 or TSC2 tumour suppressor gene, which encodes the proteins hamartin and tuberin, respectively." (PMID 23143994, 2013).
tuberous sclerosis (continued). "In humans, mutation of either the Tsc1 or the Tsc2 gene causes tuberous sclerosis complex, a multisystem genetic disease, which is commonly characterized by neurological symptoms, such as seizures, autism, mental retardation and learning disabilities." (PMID 23143994, 2013). "The importance of TSC1/TSC2 in the control of mTORC1 is revealed in tuberous sclerosis patients, where functional loss of either TSC1 or TSC2 results in non-metastatic tumors (reviewed in 10)." (PMID 24303063, 2013). "Tuberous sclerosis (TSC) is associated with germline mutations in the TSC1/Harmatin (MIM605284) and TSC2/Tuburin (MIM191092) genes." (PMID 23369289, 2013). "It is known for long that loss of function mutations in either or both of Tsc1/2 proteins cause seizures, cognitive defects and benign tumors in multiple tissues, yielding to a disease known as tuberous sclerosis." (PMID 24216995, 2013). "About 85% of cases of tuberous sclerosis complex are caused by loss of function mutations in either TSC1 or TSC2, resulting in hyperactivation of mTORC1 in affected tissues." (PMID 24379984, 2013). "There is a strong association between PEComas and tuberous sclerosis, which is due to the loss of tumor suppressor genes TSC1 or TSC2." (PMID 23984176, 2013). "Deletion of either Tsc1 or Tsc2 genes, which are mutated in patients with Tuberous Sclerosis Complex and whose protein products are indirect downstream targets of LKB1 signaling, resulted in some of the same defects observed in Lkb1 mutant mice." (PMID 22916036, 2012). "TSC1 is mutated in tuberous sclerosis, acts downstream of PTEN in the mTOR pathway and affects cortical lamination, neuronal migration and axon pathfinding." (PMID 22457638, 2012). "More than half of the renal AML are considered to be associated with tuberous sclerosis which features the loss of heterozygosity at TSC1 (9q34) and TSC2 (16p13), while it is estimated to be 5–15% in the liver." (PMID 23320180, 2012). "This is precisely the situation that exists in individuals with tuberous sclerosis since heterozygosity for TSC1 or TSC2 is causative for the disorder." (PMID 22319582, 2012). "Tuberous sclerosis (TS) is a dominant disorder produced by mutations affecting one of two proteins, TSC1 or TSC2." (PMID 22319582, 2012). "Mutations in either the Tsc1 or the Tsc2 gene can cause the pathology of the tuberous sclerosis complex." (PMID 23105973, 2012). "Tuberous Sclerosis is caused by mutations in the TSC1 or TSC2 gene and is often associated with autism, mental retardation and epilepsy." (PMID 20126541, 2010). "Tuberous sclerosis (TSC) is an autosomal dominant disease due to heterozygous mutations in TSC1 on chromosome 9q34 or TSC2 on chromosome 16p13." (PMID 19333415, 2009). "Tuberous Sclerosis Complex is genetically determined with an autosomal dominant inheritance and is caused by inactivating mutations in either the TSC1 or TSC2 genes." (PMID 19506736, 2008). "Tuberous sclerosis complex is a dominant genetic disorder produced by mutations in either of two tumor suppressor genes, TSC1 and TSC2; it is characterized by hamartomatous tumors, and is associated with severe neurological and behavioral disturbances." (PMID 17440611, 2007). "Mutations in TSC1 or TSC2 result in tuberous sclerosis, a human syndrome characterized by formation of benign tumors, or hamartomas, and a range of neurological and behavioral anomalies, including epilepsy and autism." (PMID 17440611, 2007). "Tuberous sclerosis (TSC) is caused by mutations in the tumor suppressor genes TSC1 or TSC2." (PMID 40546967, 2025). "Tuberous sclerosis (TS) is a rare autosomal dominant disorder characterized by pathogenic mutations in TSC1 or TSC2 genes, leading to the formation of hamartomas and benign tumors in the CNS or outside it (e.g., fibromas, angiofibromas, angiomyolipomas, and cardiac rhabdomyomas)." (PMID 39492623, 2025).
tuberous sclerosis (continued). "Notably, he had clinical manifestations of tuberous sclerosis, confirmed by a pathogenic germline mutation in the TSC1 gene." (PMID 40710562, 2025). "Meanwhile, human midgestation CGE interneuron progenitors are the putative cell of origin for tuberous sclerosis complex caused by germline TSC1/2 mutations, which inhibit mTOR signaling, and are associated with subependymal nodules and subependymal giant cell astrocytoma." (PMID 39495206, 2025). "In addition, the folliculin gene (FLCN) is mutated in the context of Birt–Hogg–Dube syndrome and the TSC1 or TSC2 genes are mutated in the context of tuberous sclerosis complex." (PMID 40361453, 2025). "The study aims to investigate the clinical, imaging, and molecular characteristics of patients diagnosed with tuberous sclerosis and to explore the correlation between specific genetic mutations (TSC1 and TSC2 genes) and the severity of clinical manifestations." (PMID 40364023, 2025). "Tuberous Sclerosis (TS) is a rare multisystem genetic disease characterized by autosomal dominant inheritance caused by mutations in the TSC1 (located on chromosome band 9q34) and TSC2 (located on chromosome band 16p13.3) genes, which leads to changes in cell differentiation and proliferation." (PMID 38311784, 2024). "Additionally, there is a suggestion that variants in the tuberous sclerosis genes predispose to ganglioglioma, with several polymorphisms and alterations in TSC1 and TSC2 having been identified in these tumours." (PMID 39294363, 2024). "Tuberous sclerosis (Bourneville disease) results from a mutation in the TSC1 and TSC2 genes." (PMID 38021712, 2023). "Mutations in either TSC1 or TSC2 contribute to the multisystem disorder tuberous sclerosis." (PMID 37834053, 2023). "Tuberous sclerosis complex is considered to be caused by pathogenic germline mutations (e.g., single nucleotide variations, deletions, insertions, and copy number variations) in either the TSC1 or TSC2 gene." (PMID 36732866, 2023). "Moreover, although one mutant allele of TSC1/2 is sufficient to give rise to tuberous sclerosis in patients, heterozygous animal models demonstrate subtle or no symptoms." (PMID 36340790, 2022). "It has been proposed that the haploinsufficiency of TSC1/2 could engage the pathomechanisms responsible for the formation of cortical tubers, the neuropathological hallmark of tuberous sclerosis." (PMID 36340790, 2022). "Defects in pigmentation linked to autophagy dysfunction characterize the tuberous sclerosis complex, an autosomal dominant disorder resulting from a pathogenic variant of TSC1 or TSC2 genes, which are responsible for the constitutive activation of the negative regulator for autophagy-mTOR." (PMID 36230960, 2022). "Several mutations in TSC2 and TSC1 cause tuberous sclerosis complex." (PMID 36611753, 2022). "Tuberous sclerosis is usually due to TSC1 and TSC2 mutations." (PMID 35449076, 2022). "Inactivating mutations in either TSC1 or TSC2 in the germ line cause Tuberous Sclerosis Complex, an autosomal dominant neurocutaneous disorder, characterized by skin lesions, neuropsychiatric disorders and mainly benign tumors of the brain, kidney, lung, heart, and skin." (PMID 33891611, 2021).
tuberous sclerosis (continued). "The inadvertent over-activation of mTOR also has the potential of tumorigenesis (for example resulting from the loss of tumor suppressor TSC1/2 function, as in Tuberous Sclerosis), but also loss of autophagy function, glucose intolerance via IRS-1 feedback inhibition and learning impairment." (PMID 34215308, 2021). "Since a decrease in melanocyte numbers and melanosome maturation hasbeen reported in ash-leaf macules of tuberous sclerosis patients harboringloss-of-function variants in TSC1 or TSC2, which encode upstream inhibitors of mTOR, westudied melanogenesis in patients with MTOR-related HI." (PMID 33833411, 2021). "AKT phosphorylation causes downstream inhibition of TSC1/TSC2 (Tuberous Sclerosis Complex)." (PMID 34828352, 2021). "According to the NIH, tuberous sclerosis is an autosomal dominant genetic disorder that ultimately leads to benign tumor growth in multiple organs of the body and it is cardinally seen with mutations in either TSC1 or TSC2." (PMID 32341806, 2020). "Indications of an increased risk were found for de novo tuberous sclerosis and Sturge–Weber syndrome, which suggest that maternal smoking during pregnancy might affect mutagenesis in TSC1, TSC2, and GNAQ." (PMID 31564984, 2019). "TSC1/TSC2 variants were found in 60% patients with tuberous sclerosis complex patients." (PMID 30185235, 2018). "TSC1/TSC2 variants were found in 60% of patients with tuberous sclerosis complex." (PMID 30185235, 2018). "Everolimus is relatively well tolerated with long-term treatment as has been shown in the EXIST-1 study (NCT00789828), where everolimus was used to treat tuberous sclerosis patients (germ-line mutations in TSC1/2) with subependymal giant cell astrocytomas (SEGAs)." (PMID 29156677, 2017). "Nevertheless, future studies are needed to address whether Tsc1 deficiency may cause susceptibility to autoimmune disorders or immunodeficiency disorders in tuberous sclerosis complex patients." (PMID 28079897, 2017). "Human Tsc1 mutations may result in tuberous sclerosis by causing functional impairment of the hamartin-tuberin complex." (PMID 27601261, 2016). "However, only 36% of TSC-associated AFs showed loss of expression of hamartin and/or tuberin in this study compared to an 83% mutation rate of the TSC1 or TSC2 gene in a large cohort study of tuberous sclerosis patients." (PMID 24558502, 2014). "Dysregulated TSC/mTOR signaling may play a pathogenetic role in forms of syndromic autism, such as autism associated with tuberous sclerosis, a genetic disorder caused by heterozygous TSC1 or TSC2 mutations." (PMID 25114803, 2014). "Rheb activity is controlled by its GAP Tsc1/2, which, when inactivated, cause tuberous sclerosis." (PMID 24216995, 2013). "According to the LOVD database, similar TSC1 nonsense mutations (e.g., p.Trp499Ter, p.Arg501Ter) are associated with a higher risk of early-onset tuberous sclerosis complex (TSC) manifestations, including cardiac rhabdomyomas and cortical tubers." (PMID 41142004, 2025). "Tuberous sclerosis complex (TSC) is an autosomal dominant disorder caused by mutations in TSC1 or TSC2, characterized in the kidney by angiomyolipoma (AML), renal cysts, and, less frequently, renal cell carcinoma, which together contribute to the risk of CKD." (PMID 41302105, 2025). "Loss of TSC1/2 function leads to tumor formation in various organs, an autosomal inherited disorder known as Tuberous sclerosis complex (TSC)." (PMID 39762645, 2025). "Currently, rapamycin (i.e., sirolimus and everolimus) is FDA approved for the prevention of transplant organ rejection and for anti-seizure therapy in Tuberous Sclerosis Complex (TSC; caused by variants in TSC1 or 2)." (PMID 40620657, 2025). "In humans, TSC1 variants are associated with developmental disorders and malformations, including tuberous sclerosis complex (TSC; OMIM #191100), focal cortical dysplasia syndrome (FCD, OMIM #607341), and lymphangioleiomyomatosis (OMIM # 606690)." (PMID 40217423, 2024).
tuberous sclerosis (continued). "Ultrasound combined with MRI identified 16 fetuses with intracranial sclerosing nodules, with 14 having TSC1/2 gene mutations, and 2 diagnosed with Tuberous Sclerosis Complex (TSC) postnatally." (PMID 38433754, 2024). "The International TSC Clinical Consensus Group has recommended that independent genetic identification of pathogenic variants of the TSC1 or TSC2 gene should be sufficient to diagnose tuberous sclerosis disease regardless of clinical data." (PMID 39410026, 2024). "The rapalogs everolimus and temsirolimus are used to treat tuberous sclerosis complex (TSC), which arises from TSC1/2 mutations that up-regulate the pathway, and some human cancers." (PMID 39519056, 2024). "Loss of function mutations in TSC1 result in dysregulated mTORC1 signaling and underlie a multi-system disorder known as tuberous sclerosis (TSC)." (PMID 39741564, 2024). "Tuberous sclerosis, or TSC, is a systemic neurological disorder caused by mutations in TSC1 or TSC2 that lead to benign tumors in the brain and other tissues." (PMID 36675042, 2023). "Tuberous sclerosis complex (TSC) is a multisystem genetic disorder caused by mutations in the Tsc1 gene (9q34) or the Tsc2 gene (16p13.3) encoding the tumor suppressor proteins, hamartin, and tuberin, respectively." (PMID 37371058, 2023). "Loss-of-function mutations in TSC1 or TSC2 can give rise to an autosomal dominant disorder of tuberous sclerosis complex (TSC) that invades multiple organs, such as brain, skin, heart, lungs, and kidneys." (PMID 37251941, 2023). "Hyperactive mTORC1 signaling is a clinical feature of patients with tuberous sclerosis complex (TSC) which is caused by inactivating pathogenic variants in either TSC1 or TSC2 genes, and sclerotic bone lesions have been frequently reported in TSC patients." (PMID 36060812, 2022). "This drug is beneficial for the treatment of seizures in animal models of genetic mTOR hyperactivation and in patients with tuberous sclerosis complex (TSC) caused by TSC2 or TSC1 mutation leading to mTOR hyperactivation." (PMID 35040598, 2022). "Tuberous sclerosis complex (TSC) is a neurocutaneous disorder caused by germline heterozygous loss-of-function mutations in TSC1 or TSC2." (PMID 34259631, 2021). "Presently, the MTOR inhibitor rapamycin and its analogs are the sole pathway-related drugs used clinically to treat epilepsy, primarily in tuberous sclerosis (TSC) patients with rare TSC1/2 deletion mutations which enhance downstream MTOR signaling." (PMID 34899181, 2021). "A variety of epithelial renal neoplasms have been identified both in patients with tuberous sclerosis complex (TSC) and in the nonsyndromic setting associated with somatic mutations in the TSC1 and TSC2 genes." (PMID 34680979, 2021). "Tuberous Sclerosis Complex (TSC) is a multisystem neurocutaneous disorder caused by heterozygous pathogenic variants in TSC1 (Chr." (PMID 32216820, 2020). "TSC1 mutations are associated with Tuberous Sclerosis Complex (TSC), characterized by multiple benign tumors of mesenchymal and epithelial origin." (PMID 32927859, 2020). "We have addressed this shortcoming by investigating monocytes from tuberous sclerosis (TSC) patients that feature a functional loss of the tumor suppressor TSC1/2 and a concomitant hyperactivation of mTORC1." (PMID 32849516, 2020). "Tuberous sclerosis (TSC) is a multisystem autosomal dominant genetic disorder due to loss of function of TSC1/TSC2 resulting in increased mTOR (mammalian target of rapamycin) signaling." (PMID 32973442, 2020). "Particularly, pathogenic variants in TSC1 that inhibit MTOR activity underlies the Tuberous Sclerosis Complex (TSC)." (PMID 33071758, 2020). "In approximately 85% of cases, TSC has been associated with genetic variations in two specific genes: tuberous sclerosis complex 1 (TSC1) and 2 (TSC2)." (PMID 32873234, 2020).